RARG (retinoic acid receptor gamma)
Diseases named in the same sentence as RARG in open-access papers (continued):
Sharing a sentence is not in itself a finding about the gene and the disease.
renal diseases (1 paper, 2012). "Further studies for the relationship between RARγ and the renal diseases should be conducted in the future." (PMID 23203050, 2012). "There was only one report studying the role of RARγ on the development of renal diseases." (PMID 23203050, 2012). "In the different renal diseases models, the expression of RARγ might be different." (PMID 23203050, 2012).
RARG also shares sentences with these, for which no sentence is quoted: Cirrhosis (2 papers); Anxiety (1); aspergillosis (1); astrocytoma (1); autoimmune disease (1); chondrosarcoma (1); colitis (1); coloboma (1); COVID-19 (1); depression (1); diabetes (1); Familial Woolly Hair Syndrome (1); glaucoma (1); head and neck tumors (1); heart failure (1); hemochromatosis (1); Hypotrichosis 13 (1); Multiple osteochondromas (1); mycosis (1); myelodysplastic syndrome (1); myeloproliferative neoplasm (1); nonalcoholic steatohepatitis (1); Obesity (1); pancreatic adenocarcinoma (1); prostate adenocarcinoma (1); renal agenesis (1); renal cell cancer (1); Retinal coloboma (1); retinoblastoma (1); salivary gland tumor (1).
A further 4 diseases each share a sentence with RARG in 1 paper.